YTHDF1 (YTH N6-methyladenosine RNA binding protein F1)
Diseases named in the same sentence as YTHDF1 in open-access papers (continued):
Sharing a sentence is not in itself a finding about the gene and the disease.
breast cancer (continued). "Using Western blot on previously obtained samples of breast cancer and normal breast tissue, we verified that YTHDF1 was significantly expressed in breast cancer." (PMID 38339157, 2024). "In the next section, we discussed the expression of YTHDF1 in different immune and molecular subtypes of breast cancer." (PMID 38339157, 2024). "By constructing ceRNA networks, we verified that miR-378g inhibited YTHDF1 expression in breast cancer cells, and miR-378g/YTHDF1 affected the proliferation rate of MDA-MB-231 cells." (PMID 38339157, 2024). "In breast cancer, HIF1α induced by hypoxia inhibits miR‐16‐5p, which under normal conditions targets and inhibits YTHDF1 via mRNA 3′UTR." (PMID 38545841, 2024). "In order to better understand the probable mechanism of YTHDF1 in breast cancer, we undertook gene analysis of YTHDF1 co-expression." (PMID 38339157, 2024). "According to a recent study, YTHDF1 facilitates breast cancer cells to proliferate and invade, boosting tumorigenicity and metastasis through promoting glycolysis." (PMID 39342406, 2024). "In this work, we examined the genetic alterations, functional expression levels, and contribution of YTHDF1 to the development of breast cancer." (PMID 38339157, 2024). "We used Western blot to demonstrate that YTHDF1 is substantially expressed in breast cancer tissues." (PMID 38339157, 2024). "Increasing evidence suggests that the lncRNA–miRNA–mRNA ceRNA network plays a critical role in a variety of human cancers, so we set out to analyze and build a ceRNA network involving YTHDF1 in breast cancer." (PMID 38339157, 2024). "We evaluated the relationship between the YTHDF1 expression, overall survival, and clinicopathology of breast cancer using TCGA, PrognoScan, and other datasets." (PMID 38339157, 2024). "The overexpression of FOXM1 in breast cancer cells partially offset the tumor suppressor impact of YTHDF1 silencing." (PMID 39342406, 2024). "We noted a link between YTHDF1 expression in breast cancer and immunostimulatory molecules, immunosuppressive molecules, MHC molecules, chemokines, and chemokine receptors." (PMID 38339157, 2024). "In order to comprehend the potential role of YTHDF1 in immunotherapy, we investigated the relationship between YTHDF1 expression and breast cancer immune checkpoint genes." (PMID 38339157, 2024). "The m6A regulators YTHDF1 and YTHDF3 were upregulated in breast cancer from TCGA and significantly associated with intrinsic subclasses and nodal metastasis, as well as poor prognosis of breast cancer patients." (PMID 36707507, 2023). "Increased enolase 1 (ENO1) mRNA m6A modification facilitates its binding to the m6A reader YTHDF1 and results in enhanced translation, leading to aerobic glycolysis in human lung adenocarcinoma and breast cancer." (PMID 37192910, 2023). "YTHDF1 facilitates S-phase entry, DNA replication, DNA damage repair, and accordingly, YTHDF1 downregulation enhanced the sensitivity of breast cancer cells to adriamycin and cisplatin, and Olaparib (a PARP inhibitor) by targeting E2F8." (PMID 36835633, 2023). "YTHDF1 plays a significant role in genitourinary cancers, particularly in kidney cancer, bladder cancer, common prostate cancer in males, as well as common breast cancer and cervical cancer in females." (PMID 38202722, 2023). "YTHDF1 promoted breast cancer metastasis by accelerating the translation of forkhead box M1 (FOXM1)." (PMID 36835633, 2023). "YTH N6-methyladenosine RNA binding protein 1 (YTHDF1) is a m6A-binding protein that promotes the growth of breast cancer cells in vitro and in vivo." (PMID 37790807, 2023). "YTHDF1 promotes DNA replication and damage repair; thus, knockdown of YTHDF1 re-sensitizes breast cancer cells to doxorubicin, cisplatin, and olaparib." (PMID 37790807, 2023). "In breast cancer, studies show that hypoxia up-regulates the expression of YTHDF1 that promotes cell proliferation and invasion thus driving tumorigenicity and metastasis." (PMID 36650570, 2023).
breast cancer (continued). "YTHDF1 as an oncogene facilitated the progression and invasion of breast cancer cells by inducing glycolysis." (PMID 36707507, 2023). "High levels of YTHDF1 were positively correlated with tumor size, and metastasis in breast cancer patients." (PMID 36835633, 2023). "By analyzing the level of YTHDF1 and clinical data of breast cancer, as well as clinical specimens, it demonstrated that YTHDF1 was overexpressed in cancer cells and specimens with breast cancers." (PMID 36707507, 2023). "YTHDF1 knock-down inhibits breast cancer cell proliferation, and invasion, and induces G0/G1 phase cell cycle arrest." (PMID 36650570, 2023). "YTHDF1 knockdown increased the sensitivity of breast cancer cells to Adriamycin, Cisplatin, and Olaparib and promoted Adriamycin-induced cell apoptosis, indicating that YTHDF1 contributed to chemoresistance." (PMID 35279688, 2022). "It has been reported that YTHDF1 is elevated in breast cancer samples and promotes breast cancer progression." (PMID 36077054, 2022). "The results of the GSE71862 dataset showed that the expression of YTHDF1 in breast cancer cell line MCF-7 was 1.6 times that of human normal breast cell line MCF-10A." (PMID 35197112, 2022). "We further performed a ribosome immunoprecipitation assay using Flag antibody to detect ARHGAP5 mRNA ribosome occupancy mediated by its m6A modification in breast cancer cells transfected with Flag-tagged RPL22 (ribosomal protein L22) upon YTHDF1 silencing." (PMID 36077054, 2022). "In short, our results indicate that YTHDF1 plays an important role in the maintenance of malignancy of breast cancer cells." (PMID 35319018, 2022). "Specifically, we found that YTHDF1 had a strong binding ability to the mRNA of PKM2 in breast cancer cell, which is a key enzyme in the glycolysis pathway and responsible for high glycolytic metabolism of YTHDF1-overexpressing tumors." (PMID 35319018, 2022). "Cell invasion tests also showed that PKM2 knockdown significantly inhibited the invasiveness of YTHDF1-overexpressing breast cancer cells." (PMID 35319018, 2022). "In breast cancer, the overexpression of YTHDF1, YTHDF3, and KIAA1429 predicted a poor prognosis in terms of OS." (PMID 35806168, 2022). "RT-qPCR and western blot analysis in the cell lines also suggested that the mRNA and protein expressions of YTHDF1 were significantly increased in the breast cancer cell lines." (PMID 35197112, 2022). "In the present study, we found that YTHDF1 was aberrantly expressed in breast cancer tissues by analyzing the cancer genome atlas (TCGA) database and further verified this finding via breast patient samples and cell lines." (PMID 35197112, 2022). "To verify the clinical significance of YTHDF1 for breast cancer, we collected and examined its expression as well as the clinicopathologic features in a cohort of patients." (PMID 35197112, 2022). "The regulators YTHDF1, YTHDF3 and KIAA1429 were found to be upregulated in breast cancer, and were associated with the metastasis of lymph nodes, breast cancer progression, and also were predictors of poor prognosis." (PMID 35721510, 2022). "Subsequently, CCK-8 assay, transwell, and wound healing assay were performed on breast cancer cells with sh-NC, sh-YTHDF1#2 or sh-YTHDF1#2 + FOXM1, respectively." (PMID 35197112, 2022). "Data from our clinical specimens indicated that YTHDF1 was also positively correlated with tumor size, lymph node invasion as well as distant metastasis in breast cancer patients." (PMID 35197112, 2022). "Meanwhile, YTHDF1 overexpression also significantly augmented the lung metastatic capacity of breast cancer cells, indicated by the increasing number of metastatic nodules in the YTHDF1 OV-treated group." (PMID 35319018, 2022). "FTO also promotes EMT and breast cancer lung metastasis by regulating the translational extension of KRT7 mRNA via YTHDF1/eEF-1." (PMID 36358640, 2022).
breast cancer (continued). "YTHDF1 facilitates S-phase entry, DNA replication and DNA damage repair, and accordingly YTHDF1 knockdown sensitizes breast cancer cells to Adriamycin and Cisplatin as well as Olaparib, a PARP inhibitor." (PMID 35279688, 2022). "To determine the impact of the miR-16-5p-mediated YTHDF1 inhibition on breast cancer cells, we systematically monitored the phenotypic changes of breast cancer cells after the transfection of miR-16-5p mimics and the corresponding inhibitors." (PMID 35319018, 2022). "We demonstrate that ADAR1 promotes the proliferation, migration and invasion of breast cancer cells through the METTL3/ARHGAP5/YTHDF1 axis and establish that METTL3 is one of the main targets of ADAR1 controlling biological functions." (PMID 36077054, 2022). "The integrating bioinformatics analyses were used to screen clinical relevance and dysregulated m6A “reader” protein YTHDF1 in breast cancer from TCGA databases, which was further validated in a cohort of clinical specimens." (PMID 35197112, 2022). "We further investigated the regulatory mechanisms of YTHDF1 on the malignancy of breast cancer cells and confirmed that YTHDF1 was capable of regulating glycolysis in breast cancer cells to exert tumor-driving functions." (PMID 35319018, 2022). "Our study showed that YTHDF1 was overexpressed in breast cancer cells and clinical tissues specimens." (PMID 35197112, 2022). "In breast cancer, although it has been reported that YTHDF1 expression is significantly increased in tumor tissues compared with para-cancerous tissues and is closely associated with poor prognosis, its specific mechanisms have not yet been clarified." (PMID 35197112, 2022). "At the same time, the high expression level of YTHDF1 was positively correlated with tumor size, lymph node invasion, and distant metastasis in breast cancer patients." (PMID 35197112, 2022). "We further verified the suppressing effect of YTHDF1 knockdown on breast cancer cell proliferation by EDU staining, in which the cell proliferation of the YTHDF1 siRNA group has been reduced by about 20%." (PMID 35319018, 2022). "To further elucidate the role of YTHDF1 in the glycolysis regulation network of breast cancer cells, we employed qPCR to detect the changes in glycolysis-related genes after the RIP treatment with YTHDF1 antibody." (PMID 35319018, 2022). "The result indicated that the high expression level of YTHDF1 was positively correlated with tumor size, lymph node invasion, and distant metastasis in breast cancer patients." (PMID 35197112, 2022). "Subsequently, FOXM1-WT and FOXM1-MUT plasmids were co-transfected into the breast cancer cells with Empty vector, YTHDF1-WT and YTHDF1-MUT plasmids, respectively." (PMID 35197112, 2022). "We transduced shRNAs targeting YTHDF1 into breast cancer cell lines MDA-MB-231 and MCF-7 to knock down the expression of YTHDF1." (PMID 35197112, 2022). "From a clinical perspective, YTHDF1 upregulation is frequently observed in breast cancer, but its involvement in those cancer-related events is still unclear." (PMID 35319018, 2022). "Here we report that YTHDF1 is a cancer driver capable of facilitating the proliferation and invasion of breast cancer cells as well as enhancing tumorigenicity and metastasis through promoting glycolysis." (PMID 35319018, 2022). "Several lines of evidence indicate that YTHDF1 functions as a putative tumor-promoter in breast cancer." (PMID 35279688, 2022). "YTHDF1 knockdown can significantly inhibit breast cancer cell proliferation, colony formation, invasion, and enhance cell apoptosis, leading to substantially enhanced antitumor efficacy." (PMID 35319018, 2022). "EdU cell proliferation assay also showed that after 2 h incubation with the EdU medium, the proliferation of breast cancer cells in the sh-YTHDF1 group was significantly lower than that in the sh-NC group." (PMID 35197112, 2022).
breast cancer (continued). "In silico analysis indicated that YTHDF1, an m6A binding protein, is a putative tumor promoter in breast cancer." (PMID 35279688, 2022). "When we knocked down YTHDF1 using siRNAs in breast cancer cell lines, ARHGAP5 protein level was significantly decreased, without affecting its mRNA level." (PMID 36077054, 2022). "The results showed that the effect of miR-16-5p treatment was similar to that of shRNA-YTHDF1 mediated YTHDF1 silencing effectively abolishing the growth and lung metastasis of subcutaneous breast cancer in mice." (PMID 35319018, 2022). "To understand the YTHDF1 regulatory mechanism in breast cancer tissues under clinically relevant conditions, we further investigated the impact of hypoxia on the YTHDF1 expression in breast cancer cells." (PMID 35319018, 2022). "Subsequently, a series of functional experiments confirmed that YTHDF1 promoted the proliferation and invasion of breast cancer cells in vitro and in vivo." (PMID 35197112, 2022). "Here, we assessed the correlation between YTHDF1 expression and tumor immune microenvironment in breast cancer." (PMID 34434939, 2021). "The correlations of YTHDF1 expression with immune cells and tumor mutation burden (TMB) were calculated in breast cancer samples." (PMID 34434939, 2021). "Following YTHDF1 knockdown, migrated as well as invasive abilities of breast cancer were investigated in breast cancer." (PMID 34434939, 2021). "Our data showed that YTHDF1 knockdown distinctly lowered the expression of Axin2, c-myc, β-catenin, and cyclin D1 in MCF-7 cells, confirming that YTHDF1 participated in the activation of WNT pathway in breast cancer." (PMID 34434939, 2021). "recently showed that YTHDF1 and YTHDF3 aberrations were associated with metastasis and predicted poor prognosis in breast cancer patients." (PMID 34804948, 2021). "Sixteen up-regulated and down-regulated genes were identified between high and low YTHDF1 expression breast cancer samples." (PMID 34434939, 2021). "Our experiments confirmed that silencing YTHDF1 suppressed migrated and invasive capacities of breast cancer cells." (PMID 34434939, 2021). "The HPA analysis also validated that YTHDF1 was prognostic, and its high mRNA expression was unfavorable in 1,075 breast cancer samples (p = 0.0008)." (PMID 34804948, 2021). "to analyze the expression of YTHDF1 in breast cancer tissues." (PMID 38339157, 2024). "The results revealed that YTHDF1 was overexpressed in breast cancer patients." (PMID 38339157, 2024). "Additionally, our knowledge of the intrinsic mechanism is still limited, and more research is required to confirm YTHDF1’s potential involvement in breast cancer immunity." (PMID 38339157, 2024). "The overexpression of YTHDF1 in breast cancer indicates a bad prognosis." (PMID 38339157, 2024). "To summarize, the increased expression of YTHDF1, one of the main readers in m6A, may be a significant factor in the advancement and a useful indicator of predicting breast cancer and its prognosis." (PMID 38339157, 2024). "In breast cancer, YTHDF1 formally influences immunotherapy efficacy through the WNT pathway." (PMID 39199429, 2024). "YTHDF1 is highly expressed in breast cancer and could be a reliable biomarker for breast cancer’s poor prognosis and tumor immunity." (PMID 38339157, 2024). "We validated that YTHDF1 expression was elevated in breast cancer tissues." (PMID 38339157, 2024). "Furthermore, YTHDF1 is predicted to be a promising target in breast cancer immunotherapy since it regulates the ceRNA network and has a specialized function in tumor immunology and breast cancer prognosis." (PMID 38339157, 2024). "Elevated expression levels of YTHDF1 have been reported in gastric, colon, and breast cancer." (PMID 38328550, 2024). "It raises the prospect that YTHDF1 might serve as a biological marker for the detection of breast cancer and have a specific role in immunomodulatory processes." (PMID 38339157, 2024).
breast cancer (continued). "Our findings indicate that YTHDF1 is a critical component of the m6A regulatory proteins in breast cancer and may have a particular function in the immunological microenvironment." (PMID 38339157, 2024). "Secondly, while we believe that YTHDF1 expression may play an important role in the immune process of breast cancer, the correlation between YTHDF1 and tumor purity and TICs was not statistically significant." (PMID 38339157, 2024). "A Western blot showed that YTHDF1 was highly expressed in breast cancer tissues." (PMID 38339157, 2024). "Furthermore, we explored how YTHDF1 expression affected breast cancer immunity and molecular subtypes using the TISIDB website." (PMID 38339157, 2024). "Similarly, YTHDF1 is elevated in breast cancer cells and clinical tissue specimens and related to tumor size, lymph node invasion, and distant metastasis in breast cancer patients." (PMID 36650570, 2023). "All the results demonstrated that YTHDF1 may be an effective target for clinical therapy of breast cancer." (PMID 36707507, 2023). "Additionally, YTHDF1 has been found to regulate the promotion of S phase entry in breast cancer by modulating the cell cycle proteins E2, CDK2, P21, and PCNA." (PMID 38202722, 2023). "Furthermore, YTHDF1 induced the progression and metastasis of breast cancer by accelerating the translation m6A-modified mRNA of FOXM1." (PMID 36707507, 2023). "However, co-transfection of miR-16-5p mimics with pCDNA3.1-YTHDF1 × FLAG plasmids restored the protein level of YTHDF1 in breast cancer cells (Original western blot data 6, 7)." (PMID 35319018, 2022). "Taken together, these data suggested that YTHDF1 knockdown blocks the proliferation, migration, and invasion of breast cancer cells, but that could be rescued by FOXM1 overexpression simultaneously." (PMID 35197112, 2022). "Based on the experimental results, we revealed that the YTHDF1-mediated m6A methylation modification could be a promising target for the development of more advanced breast cancer therapies with enhanced efficacy and selectivity." (PMID 35319018, 2022). "For example, a growing body of literature strongly suggested that YTHDF1 may regulate the immune microenvironment of breast cancer, influencing tumor growth as well as immunotherapy efficacy." (PMID 36091006, 2022). "Moreover, we found that knockdown of YTHDF1 inhibited cell proliferation, colony formation, migration and invasion in breast cancer cell lines." (PMID 36077054, 2022). "Our study reveals a novel YTHDF1/FOXM1 regulatory pathway that contributes to metastasis and progression of breast cancer, suggesting that YTHDF1 might be applied as a potential biomarker and therapeutic target." (PMID 35197112, 2022). "Third, YTHDF1 promotes breast cancer cell growth in vitro and in vivo." (PMID 35279688, 2022). "In this study, miR-16-5p acts as a tumor suppressor by selectively inhibiting YTHDF1, which could be exploited as a potential therapy for breast cancer." (PMID 35319018, 2022). "Moreover, ADAR1 edits the nearby ORF stop codon of METTL3 mRNA, leading to its binding site changing to miR-532-5p and resulting in increased METTL3 protein, which further targets ARHGAP5 to promote breast cancer progression in a YTHDF1-dependent manner." (PMID 36077054, 2022). "To investigate the role of YTHDF1 in the development of human breast cancer, we first analyzed the expression of YTHDF1 in breast cancer at transcriptome and protein expression levels using The Cancer Genome Atlas (TCGA) dataset and Clinical Proteomic Tumor Analysis Consortium (CPTAC)." (PMID 35319018, 2022). "We further verified the role of the YTHDF1/FOXM1 axis in breast cancer progression." (PMID 35197112, 2022). "To further elucidate the potential regulatory role of YTHDF1 in breast cancer, we genetically depleted YTHDF1 in breast cancer cells and systematically monitored the phenotypical changes after the transfection of two YTHDF1-targeting siRNAs (siYTHDF1 1 and siYTHDF1 2)." (PMID 35319018, 2022).